ATP2A1 (ATPase sarcoplasmic/endoplasmic reticulum Ca2+ transporting 1)
Diseases named in the same sentence as ATP2A1 in open-access papers (continued):
Sharing a sentence is not in itself a finding about the gene and the disease.
tumor (9 papers, 2019 to 2025). "Previous studies have also shown that ATP2A1 is a pathogenic molecule in tumor tissues." (PMID 35783262, 2022). "Subsequently, paired analysis was performed, and we found that the expression level of ATP2A1 in tumor samples of the same patient was significantly higher than that in the paracancerous samples." (PMID 35783262, 2022). "Patients with M0 stage tumors showed only CACNA1H, SLC24A3 and NALCN associated with OS differences, while ATP2A1, ATP13A2, TRPC1, and NALCN proved to be significantly associated with OS in the N1–N3 tumor stage patient subgroup." (PMID 31083561, 2019). "Altogether, these results demonstrate that ATP2A1 may impact tumor progress partly due to the immune aspect." (PMID 35783262, 2022). "In addition, we also found that a high ATP2A1 methylation level was negatively correlated to the tumor stage." (PMID 35783262, 2022). "Expression levels of ATP2A1 were negatively associated with monocytes and macrophages, and positively correlated with B-cell infiltration, while BET1 demonstrated positive correlations only with tumor infiltration by macrophages and Th1 cells in CHOL." (PMID 34831096, 2021). "In addition, the analysis of clinically related properties found that the decrease of the methylation status of the methylation site of ATP2A1 could promote tumor metastasis." (PMID 35783262, 2022). "The four candidate genes (CACNA1S, ATP2A1, RYR1, and MYLK3) of Ca2+ signaling have special functions in tumor progression." (PMID 35509066, 2022). "However, we compared expression profiles between tumor grades and found that SNX15, ATP2A1, PDCD10, BET1, and HMGA2 expressions were significantly (all p < 0.05) associated with tumor stages." (PMID 34831096, 2021). "Suggestively, our results indicated that SNX15, ATP2A1, PDCD10, BET1, and HMGA2 could serve as a biomarker signature of tumor progression and metastasis in CHOL patients." (PMID 34831096, 2021). "It works together with the ER channel proteins, ATP2A1 and RYR1; regulates the intracellular calcium concentration, then affects the concentration and function of MLYK3 downstream through the calcium/calmodulin pathway, and finally affects the formation and biological behavior of tumor cells." (PMID 35509066, 2022).
myopathy (8 papers, 2016 to 2026). A disease of the muscle in which the muscle fibers do not function properly. "The ROC curve analysis showed that MYH1, ATP2A1, TNNT3, and MYLPF showed good diagnostic performance for RYR1 mutation-associated myopathies." (PMID 35692882, 2022). "Impacted by their good diagnostic properties in RYR1 mutation-associated myopathies, a hypothesis was proposed that MYH1, ATP2A1, TNNT3, and MYLPF are likely to serve as biomarkers for diagnosing RYR1 mutation-associated myopathies." (PMID 35692882, 2022). "MYH1 (AUC: 0.856) achieved the maximum diagnostic value in RYR1 mutation-associated myopathies samples, and the diagnostic values of other genes included the following: TNNT3 (AUC: 0.840), MYLPF (AUC: 0.786), and ATP2A1 (AUC: 0.765)." (PMID 35692882, 2022). "Four skeletal muscle tissue-specific genes were identified, including MYH1, TNNT3, MYLPF, and ATP2A1, as the potential biomarkers for diagnosing and treating RYR1 mutation-associated myopathies, which provided insights into the transcriptome-level development mechanism." (PMID 35692882, 2022).
infection (4 papers, 2014 to 2023). The state of being infected such as from the introduction of a foreign agent such as serum, vaccine, antigenic substance or organism. "Like Tnni2, Atp2a1 mRNA was not apparently upregulated, but we nonetheless detected scattered Atp2a1 protein expression in atrial cardiomyocytes, likely reflecting mosaic infection." (PMID 36076959, 2022). "The relatively greater impairment of atrial function compared with the ventricles may indicate a higher rate of infection in the atria, where we detected ectopic expression of Atp2a1, in contrast with the ventricles where we did not." (PMID 36076959, 2022). "Atp2a1 and Tnni2 did not appear to be upregulated, but this likely reflects the lower detection background, since the AAV9 infection was mosaic." (PMID 36076959, 2022).
metabolic disease (1 paper, 2020). A congenital disorder (due to inherited enzyme abnormality) or acquired (due to failure of a metabolically important organ) disorder resulting from an abnormal metabolic process. "Interestingly, when compared to Viv chow, both SO + CO and PL + CO diets caused dysregulation of 8 to 22 genes associated with metabolic disease, whereas the CO diet yielded only 2 disease-related genes (Atp2a1 and Rgs16), both of which are linked to inflammation." (PMID 31912136, 2020).
ATP2A1 also shares sentences with these, for which no sentence is quoted: McArdle disease (3 papers); respiratory failure (3); genetic disease (2); Insulin resistance (2); muscle disorder (2); actinomycosis (1); Allergy (1); amyotrophic lateral sclerosis (1); bipolar disorder (1); chronic kidney disease (1); Cirrhosis (1); co-infection (1); colon adenocarcinoma (1); common variable immunodeficiency 3 (1); congenital myopathy (1); coronary artery disease (1); Cyanosis (1); follicular thyroid adenoma (1); follicular thyroid carcinoma (1); heart disease (1); heart failure (1); hepatoma (1); immunodeficiency 52 (1); melanoma (1); metabolic syndrome (1); microcephaly (1); myocarditis (1); myonecrosis (1); myositis (1); myotonic dystrophy type 2 (1).
A further 9 diseases each share a sentence with ATP2A1 in 1 paper.